CXCL8 (C-X-C motif chemokine ligand 8)
Diseases named in the same sentence as CXCL8 in open-access papers (continued):
Sharing a sentence is not in itself a finding about the gene and the disease.
tumor (continued). "CXCL8 also recruits MDSCs that inhibit anti-tumor T cell function via the induction of Tregs and production of immunosuppressive cytokines including IL-10 and transforming growth factor beta (TGF-β)." (PMID 30870978, 2019). "The contacts between the tumor cells and the MSCs set the stage for the activities of TNFα which increased CXCL8 production, in a process that was entirely dependent on p65 activation (Figure 3B2)." (PMID 31105691, 2019). "A number of studies have indicated the functional role of chemokines, including CXCL1 and CXCL8, in the tumour microenvironment." (PMID 31147602, 2019). "Emerging data suggest that tumor-produced IL-8 (CXCL8) plays an important role in recruiting neutrophils and monocytes into the TME of many cancer types." (PMID 31402908, 2019). "Knock-down of Interleukin-8 (IL-8, or CXCL8), which can be produced by macrophages, was shown to inhibit tumor growth in colorectal liver metastasis." (PMID 31263976, 2019). "We demonstrated significant differences between CXCL-8 concentrations and depth of tumor invasion (T factor) in OC patients and OSCC subgroup." (PMID 30820705, 2019). "Neutrophils are chemotactically attracted to tumor cells through secretion of IL-8 (also known as CXCL8)." (PMID 31852512, 2019). "Overall, tumor:stroma interactions set the stage for Notch1 activation by pro-inflammatory signals, leading to CXCL8 induction and consequently to pro-metastatic activities." (PMID 31105691, 2019). "Compared with the levels of expression of the matched normal tissues, the levels of CXCL8 mRNA were found to be one of the most upregulated genes among tumor tissues (log2 Fold change = 3.45, p-adjust value = 2.71×10-8)." (PMID 32038715, 2019). "The RNA-seq profiles revealed that the levels of CXCL8 mRNA in tumor, compared with those of normal tissues, were significantly increased in patients with early-stage or advanced-stage in CRC." (PMID 32038715, 2019). "The tumor-stroma-inflammation network was found in our study to strongly induce the expression of the pro-metastatic chemokines CXCL8, CCL2 and CCL5." (PMID 31031757, 2019). "Production of CXCL1 and CXCL8 by a variety of tumor cell types has been shown to be induced by the conditioned media obtained from senescent human peritoneal mesothelial cells." (PMID 30870978, 2019). "Published studies indicate that the p300-mediated process of CXCL8 induction reflected interaction with the NF-κB pathway, further supporting our findings on p65-Notch1 cross-talk that regulates CXCL8 induction in our tumor-stroma-inflammation network in TNBC." (PMID 31105691, 2019). "The percentage of elevated concentrations (diagnostic sensitivity) of CXCL-8 (86%) was higher than that of CRP (82%) and far higher than those of the classical tumor markers: SCC-Ag (74%) and CEA (18%)." (PMID 30820705, 2019). "CXCL8 is also induced by hypoxia as a hypoxia-inducible factor 1-independent pathway to preserve tumor angiogenesis as a compensatory pathway of VEGF." (PMID 30691207, 2019). "CXCL8 is also important for tumor progression and the early up-regulation of the cytokine supports this thesis." (PMID 31261642, 2019). "CXCL8 has well-known pro-tumorigenic effects in several human cancers including the thyroid ones and its targeting was shown to hamper tumor progression." (PMID 30867499, 2019). "Most importantly, when p65 was down-regulated in both cell types together, almost no CXCL8 was produced by the “Contact” co-cultures indicating that p65 was the master regulator of CXCL8 expression in this setting of the tumor-stroma-inflammation network." (PMID 31105691, 2019). "The diagnostic sensitivity, negative predictive value and the area under ROC curve (AUC) of CXCL-8 were higher than those of classical tumor markers." (PMID 30820705, 2019). "Triple-negative breast cancer (TNBC) cells secrete CXCL8, which activates CXCR2 in tumor-associated fibroblasts and tumor-associated macrophages." (PMID 31788042, 2019).
tumor (continued). "In the present study, we established significant correlations between serum CXCL-8 concentrations, depth of tumor invasion (T factor) and CRP concentrations in OC patients and the OSCC subgroup." (PMID 30820705, 2019). "This is achieved by paracrine signaling from tumor cells to the stroma via secretion of cytokines, such as interleukin-6 (IL-6) and IL-8 (CXCL8), which promote invasion, neovascularization, and inflammatory responses." (PMID 30353166, 2019). "We began this part of the study by asking which of the two cell types, the MSCs and/or the tumor cells, contribute/s to CXCL8 expression in TNFα-stimulated MDA-MB-231:MSC “Contact” co-cultures." (PMID 31105691, 2019). "In stromal fibroblasts, miR-20a (ranked second in the WINMDA forecast list) can modulate chemokine C–X–C ligand 8 (CXCL8) function, thereby influencing tumor latency." (PMID 30597923, 2018). "In glioma, high level of CXCL8 is found in tumor cells, and correlated with increased neutrophil infiltration and tumor progression." (PMID 30619286, 2018). "We also identified transcriptional upregulation of PDGFA and CXCL8/IL8 and corresponding increased secretion of PDGF-AA and IL-8, two factors that can influence tumor inflammatory cell content and vascular proliferation." (PMID 29643433, 2018). "Based on these data we decided to focus on miR-20a and miR-20b as prime candidates to modulate CXCL8 expression during tumor progression." (PMID 29560130, 2018). "Conversely, tumor latency is increased, when miR-20a levels are elevated resulting in decreased CXCL8 protein secreted into the tumor microenvironment." (PMID 29560130, 2018). "Based on the multifaceted tumor-promoting effects of CXCL8, the possibility to use this chemokine as a tumor biomarker appeared a fascinating perspective." (PMID 29977225, 2018). "Granulocytic MDSCs, mainly composed by different subsets of neutrophils, express CXCR1 and CXCR2, and are recruited to the tumor by CXCL8, produced by tumor cells or by Treg." (PMID 30319638, 2018). "This process is exemplified by the observation that in human gastrointestinal cancer the concentrations of CXCL8 in tissues and in the circulation are correlated with the amount of new blood vessels within the tumor." (PMID 29977225, 2018). "Specifically, patients with advanced tumor stage, higher tumor grade, and bigger tumor size exhibit higher CXCL8 mRNA levels." (PMID 29636079, 2018). "Since CXCL8 was the chemokine most consistently induced by IM, we next assessed CXCL8 protein concentrations in conditioned media of the tumor cell lines UD-SCC 8 and HeLa treated with IM or medium controls by ELISA." (PMID 30266096, 2018). "The inhibition of CXCL8 secretion by this compound would account for the decrease of tumor neoangiogenesis and vascularization in vivo." (PMID 29977225, 2018). "Among the identified microRNAs, miR-20a/b was further investigated as its stromal expression levels inversely correlated with the amounts of CXCL8 secreted and predicted fibroblast tumor-promoting activity." (PMID 29560130, 2018). "The presence of a neutrophil infiltrate within the tumor of nude mice transplanted with KHM-5M cancer cells strongly supported a role for CXCL8 produced by neoplastic thyroid cells in the recruitment of neutrophils at the tumor site." (PMID 29977225, 2018). "CXCL8 can function in both a paracrine manner to alter the immune composition of the TME as well as in an autocrine manner to regulate tumor cell EMT and invasion." (PMID 30185911, 2018). "CXCL8 secreted from tumor cells via an autocrine manner acts on tumor microenvironment and enters the peripheral blood." (PMID 29636079, 2018). "Our study proved that CXCL8 acted as an unfavorable factor promoting to tumor progression and poor prognosis of ADC, while DACH1 antagonized CXCL8 to provide a favorable survival of ADC patients." (PMID 29636079, 2018).
tumor (continued). "The detrimental effect of CXCL8 is further supported by its upregulation of MMPs from tumor cells hence increasing their potential for metastasis." (PMID 29850390, 2018). "Based on the results of the ADC xenograft mice model, DACH1 efficiently inhibited the expression of CXCL8 and the pro-proliferative factors, such as cyclin D1 and Ki-67, which in turn significantly retarded the tumor growth." (PMID 29636079, 2018). "Neutrophils expressing CXCR1 and CXCR2 are attracted to the tumor site following a gradient of concentration of CXCL8 secreted by tumor cells." (PMID 29977225, 2018). "Neutrophils are stimulated to release immunosuppressive arginase 1 by supernatants from tumor cells in a CXCL8-dependent manner, and knockdown of CXCL8 blocks this effect." (PMID 30619286, 2018). "Given the crucial importance of tumor-related inflammatory microenvironment in determining tumor progression, it appears likely that research to address the issue of lowering CXCL8 secretion will continue in the future." (PMID 29977225, 2018). "The action of CXCL8 is mainly exerted through the recruitment of neutrophils (moving from blood vessels to the tumor site), which enable the migration of tumor cells." (PMID 29977225, 2018). "Since IL-17 has no direct effect on the proliferation of ECs, the proangiogenic effect is likely to be exerted through the enhancement of VEGF and/or CXCL8 by tumor cells." (PMID 29675018, 2018). "In the context of cancer, CXCL8 acts as an important multifunctional cytokine to modulate proliferation, invasion, and migration of tumor cells via an autocrine or paracrine manner." (PMID 29636079, 2018). "Significantly higher levels of CXCL8 were detected in supernatants of tumor cell lines treated with IM as compared to supernatants of primary human epithelial keratinocytes." (PMID 30266096, 2018). "Patients with big tumor size (T3-T4) had upregulated CXCL8 expression compared with patients with small tumor size (T1-T2) (p = 0.006)." (PMID 29636079, 2018). "For example, PTEN dysfunction has been shown to increase the expression and signaling of pro-inflammatory chemokine CXCL8 in prostate cancer cells that resulted in a coordinated response of both tumor and stromal cells." (PMID 29946544, 2018). "RNA sequence analysis of myeloid-driven tumorigenic BPH-TW cells revealed increased expression of IL-1α and its target genes CXCL1 and CXCL8. shRNA knockdown of IL-1α in the transformed BPH-TW tumor cells resulted in decreased tumor growth." (PMID 29502208, 2018). "C-X-C motif ligand 8 (CXCL8), known as a proinflammatory chemokine, exerts multiple effects on the proliferation, invasion, and migration of tumor cells via the autocrine or paracrine manner." (PMID 29636079, 2018). "The result showed that CXCL8 mRNA expression was positively correlated with tumor stage at mRNA level (p = 0.0009)." (PMID 29636079, 2018). "The results showed that the mRNA profile of CXCL8 was dramatically higher in tumor tissue than normal tissue (p < 0.0001)." (PMID 29636079, 2018). "Instead, a successful anti-CAC therapy also needs to involve strategies to prevent colitic fibroblasts from secreting tumor-promoting factors such as CXCL8 into the microenvironment." (PMID 29560130, 2018). "In our research, we focused on the potential role of metformin in CXCL8 expression, the key factor that orchestrates tumor microenvironment formation." (PMID 29147073, 2017). "CXCL1, CXCL5 and CXCL8 were overall the most abundant chemokines present in the RCC tumor supernatants." (PMID 28923105, 2017). "It has been reported that lactic acid drives endothelial cell migration and tube formation by triggering the phosphorylation/degradation of IκBα and by stimulating the NF-κB/IL-8 (CXCL8) pathway, promoting tumour angiogenesis." (PMID 28165036, 2017).
tumor (continued). "Clinical studies showed that patients receiving chemotherapy have increased NFκB activity and cytokine expression, such as CXCL8, and a high level of CXCL8 compromises the docetaxel-mediated apoptosis of tumor cells." (PMID 29142311, 2017). "CXCL8 is overexpressed in different human carcinomas and tumor cell lines, such as breast, colon, cervical, lung, brain, prostate, ovarian and renal cell carcinomas, acute myelogenous and B-cell lymphocytic leukemia, melanoma and Hodgkin’s disease." (PMID 29340117, 2017). "The presence of a variety of factors including inflammatory cytokines [TNF-α, CXCL8 (interleukin-8), and CXCL1 (GRO-α)] have been implicated in mediating both innate and acquired resistance to taxanes and/or platinating agents in tumor cell lines." (PMID 28915246, 2017). "Interleukin-8, also known as CXCL8, plays a vital role in cancer progression by initiating angiogenesis; recruiting monocytes to the tumor site; and enhancing the proliferation, survival, and metastasis of cancer cells." (PMID 28955335, 2017). "Our in vivo tumor reversal experiments using the PI3K inhibitor, LY294002, demonstrated not only tumor regression via apoptosis but also a state of chronic inflammation as evidenced by the increased expression of the inflammatory chemokine, CXCL8." (PMID 28881576, 2017). "The association between CXCL8, CXCL1 and tumor metastasis has been thoroughly described in previous studies." (PMID 28356111, 2017). "We observed CXCL8 expression in normal squamous epithelia and tumor nests, particularly in the invasive area, by immunohistochemistry." (PMID 29285315, 2017). "We detected a concentration gradient for the CXCR2 ligands CXCL1, CXCL2, CXCL5, CXCL6 and CXCL8 between the plasma and the tumor tissues of patients with primary RCC." (PMID 28923105, 2017). "Among these, CXCL1, CXCL5, and CXCL8 have been described to stimulate PCa cell proliferation, cell survival, migration, invasion, and angiogenesis, thus promoting tumor growth as well as metastasis." (PMID 29142311, 2017). "Another study on hepatocellular carcinoma indicated importance of CXCL16 and its receptor CXCR6 in neutrophil recruitment and tumor progression due to its ability to stimulate the release of CXCL8 by tumor cells." (PMID 29340117, 2017). "Human CXCL8 (IL-8) is one of the best studied neutrophil chemoattractants with respect to human tumor biology." (PMID 29340117, 2017). "For the calcium flux assay, NK cells transduced with CXCR2 or the control NGFR were stimulated with recombinant CXCL8 or conditioned RCC tumor supernatants." (PMID 28923105, 2017). "In the CXCR-positive tumor cells, the secreted CXCL8 acted in an autocrine manner promoting tumor cell proliferation, migration, and angiogenesis." (PMID 29147073, 2017). "CXCL8 promotes tumor microenvironment construction through recruiting leukocytes and endothelial progenitor cells that are involved in angiogenesis." (PMID 29147073, 2017). "CCL2, CCL3, CCL4, CCL5, CXCL1, CXCL8 etc. are chemokines involved in the recruitment of MDSC to tumour microenvironment." (PMID 28275390, 2017). "In clinical studies, patients with high CXCL8 levels are reported to have poorer prognosis: lower survival rate, higher liability of tumor recurrence after surgery excision, and higher liability of tumor metastasis to distant organs." (PMID 29147073, 2017). "In recent decades, CXCL8 has been suggested to serve as a multifunctional cytokine to regulate tumor cells proliferation, invasion, and migration." (PMID 28883082, 2017). "Several circulating cytokines, including hepatocyte growth factor (HGF), TGF-beta, CXCL8 and CXCL12, have been implicated as contributors to anoikis signaling in some kinds of tumor cells." (PMID 28430645, 2017).
tumor (continued). "Semaphorins were discovered as axonal growth cone guidance molecules; semaphorin 3B induced CXCL8 (IL-8) production by tumor cells in a Neuropilin-1 dependent manner, which recruited TAMs fostering a prometastatic environment surprisingly with tumor reduction." (PMID 28197019, 2017). "Thus, it still remains controversial how CXCL8 would influence the metastases; however, our results showed that reductions in the expression of CXCL8 is associated with tumor progression and metastases, indicating that these cytokines could possibly play roles as tumor suppressors and biomarkers." (PMID 28745433, 2017). "Another recent study showed that human metastatic melanoma cells entrapped in the lungs secrete CXCL8 to attract neutrophils, which promotes tumor cell tethering to the vascular endothelium." (PMID 29340117, 2017). "Immunofluorescence demonstrated that a large fraction of the CXCL8-positive spindle cells co-expressed with the macrophage marker CD11b in the tumor nests and stroma of human ESCCs." (PMID 29285315, 2017). "In contrast, CXCL8/IL-8 which is over expressed in tumours of the Take group and CXCL12/SDF-1alpha are found in some mesenchymal regulons and have been shown to cooperatively promote invasiveness and angiogenesis in pancreatic cancer." (PMID 28588211, 2017). "They classified ESCC tissues into two groups, negative and positive, based on the product of the intensity of immunostaining and the percentage of positive tumor cells expressing CXCL8 and CXCR2." (PMID 29285315, 2017). "The chemokine CXCL8, also known as interleukin-8 (IL-8) and its receptors are involved in oncogenesis and in tumor progression, invasion, and metastasis." (PMID 27019857, 2016). "TNF-α, released in the tumour microenvironment, is linked with tumour progression inducing degranulation of the neutrophils, releasing VEGF and favouring angiogenesis with the production of CXCL8 and CXCL1." (PMID 26913068, 2016). "Given the advantages of lowering this chemokine levels in the tumor microenvironment further efforts targeting CXCL8 inhibition appear worthwhile." (PMID 27555670, 2016). "It is known that the spleen is the site of localization of TAM and TAN precursors, from where they physically relocate to the tumor stroma, and that CXCL8 (IL-8), a chemoattractant for neutrophils, is also chiefly responsible for the recruitment of TANs." (PMID 26966341, 2016). "CXCL8 is a key regulator of immune cells infiltration into the tumor microenvironment promoting cancer invasion and metastasis." (PMID 27555670, 2016). "Targeting and/or lowering CXCL8 concentrations within the tumor microenvironment would produce a therapeutic benefit." (PMID 27555670, 2016). "CXCL8 is detected in serum and tissue specimens from patients with solid tumors, its circulating levels being correlated with tumor size, depth of infiltration, stage, and prognosis." (PMID 27555670, 2016). "Stimulation of tumor cells via CXCR6 induces the production of CXCL8 which induces the recruitment of neutrophils." (PMID 27618112, 2016). "In high-grade tumours, CXCL8 expression in malignant epithelium was also observed for five out of nine non-obese patients and for all obese patients." (PMID 27241286, 2016). "CXCL8 is produced in abundance by tumour cells, which once released into the microenvironment represent a potent chemo-attractant of neutrophils within the tumour." (PMID 26913068, 2016). "In this context, it is important to acknowledge that higher PTX3 and CXCL8 blood levels in patients with recurrence of disease in this study represent a mere phenomenological evidence of the inflammatory reaction at the tumor site." (PMID 26859579, 2016). "IL-8, alternatively known as CXCL8, is a proinflammatory chemokine highly related to the progression of cancer, since many studies have shown overexpression of IL-8 by tumor cells." (PMID 26000020, 2015).